CHRNA4 (cholinergic receptor nicotinic alpha 4 subunit)
Diseases named in the same sentence as CHRNA4 in open-access papers (continued):
Sharing a sentence is not in itself a finding about the gene and the disease.
Cognitive impairment (27 papers, 2011 to 2025). Abnormal cognition is characterized by deficits in thinking, reasoning, or remembering. "Parasuraman and collaborators have taken a cognitive neuroscience approach to study effects of genes involved in risk of AD (APOE) or mechanisms involved in cognitive deficit in AD (cholinergic genes—CHRNA4)." (PMID 22693679, 2012).
Anxiety (26 papers, 2010 to 2025). Intense feelings of nervousness, tension, or panic often arise in response to interpersonal stresses. "Corroborating our finding, previous studies showed the association of the CHRNA4 rs1044396 T allele with a protective effect in different phenotypes, such as: lower levels of depression, anxiety, and emotional instability, and lower propensity for ND." (PMID 25774163, 2015). "CHRNA4 encodes alpha-4 nicotinic acetylcholine receptor subunits and knockout mice show heightened anxiety-like behavior." (PMID 20805988, 2010). "Polymorphisms in the human CHRNA4 gene, which encodes the α4 nAChR subunit, has been linked to anxiety and emotional lability, and α4β2 nAChRs have been linked to anxiety in a number of studies." (PMID 39763615, 2024). "CHRNA4 also impacts arousal, anxiety, and memory, and CHRM2, is important in learning, memory and higher order brain functions." (PMID 33897478, 2021). "Mice null for chrnA4, display an increased anxiety, and variation in CpG methylation of chrnA4 in ventral-hippocampal granule cells and neurons is also linked to anxiety." (PMID 28928767, 2017).
Alzheimer disease (25 papers, 2011 to 2024). A progressive, neurodegenerative disease characterized by loss of function and death of nerve cells in several areas of the brain leading to loss of cognitive function such as memory and language. "As for example, Varenciline (an approved drug for smoking cessation) or AZD1446 (phase II completed for cancer and Alzheimer's disease) are agonists for CHRNA4 (cholinergic nicotinic receptor) and can be tested whether it would be useful to prevent or delay the lymph node metastasis in CRC." (PMID 22363777, 2012).
autosomal dominant nocturnal frontal lobe epilepsy (20 papers, 2010 to 2025). A seizure disorder characterized by intermittent dystonia and/or choreoathetoid movements that occur during sleep. "Mutations in CHRNA4 have been reported with nocturnal frontal lobe epilepsy type 1." (PMID 36539902, 2022). "These clinical features are similar to BFNE caused by KCNQ2 variations and are different from those of autosomal-dominant nocturnal frontal lobe epilepsy (ADNFLE) caused by CHRNA4 variations and developmental and epileptic encephalopathy 33 (DEE33) caused by EEF1A2 variations." (PMID 35557555, 2022). "Fast ionotropic nicotinic acetylcholine receptor (nAChR) subunit genes, α2 (Chrna2), α4 (Chrna4) and β2 (Chrnb2), have been affiliated with autosomal dominant nocturnal frontal lobe epilepsy (ADNFLE) when mutated." (PMID 28825447, 2017). "Autosomal dominant nocturnal frontal lobe epilepsy (ADNFLE) is caused by mutations in the CHRNA4, CHRNA2, CHRNB2, or KCNT1(Slack) genes." (PMID 25784856, 2015). "Autosomal dominant nocturnal frontal lobe epilepsy (ADNFLE), now renamed (AD)SHE, or (Autosomal dominant) sleep-related hypermotor epilepsy, was first linked to a missense mutation on CHRNA4 (α4S248F)." (PMID 37626860, 2023). "Mutations in KCNQ2 and CHRNA4 have been identified in individuals with benign familial neonatal convulsions (BFNC) and autosomal dominant nocturnal frontal lobe epilepsy (ADNFLE), respectively." (PMID 20805988, 2010).
depression (20 papers, 2012 to 2024). "An association between the variant (A) allele of CHRNA4 rs1044396 and psychiatric illnesses such as depression, anxiety disorders and certain other addictions was reported." (PMID 35222535, 2022). "Human genetic studies have indicated that mutations in the CHRNA4 gene, encoding the α4 subunit, is linked to a vulnerability to both alcoholism and depression." (PMID 26136145, 2015). "Significant associations between CHRNA4 and depression and loneliness were demonstrated in a study of elderly population." (PMID 24498031, 2014). "Furthermore, polymorphisms in the CHRNA4 gene have been linked to major depression and negative emotionality." (PMID 26136145, 2015).
Parkinson disease (16 papers, 2012 to 2025). A progressive degenerative disorder of the central nervous system characterized by loss of dopamine producing neurons in the substantia nigra and the presence of Lewy bodies in the substantia nigra and locus coeruleus. "CHRNA4, MAOB and CHRM2 are targets for the treatment of Parkinson’s disease." (PMID 35566179, 2022).
frontal lobe epilepsy (8 papers, 2011 to 2025). A localization-related (focal) form of epilepsy characterized by seizures which arise in the frontal lobe. "CHRNA4 belongs to the ligand-gated ion channel family, and its mutations cause nocturnal frontal-lobe epilepsy." (PMID 36835631, 2023). "Chrna4 encodes a subunit of the nicotinic acetylcholine receptor whose mutations are associated with nocturnal frontal lobe epilepsy." (PMID 34177758, 2021). "Ever since, CHRNA2 and CHRNB2, as well as an additional CHRNA4 mutation, have been reported in sleep-related FLE (frontal lobe epilepsy)." (PMID 36835631, 2023). "For example, mutations in the CHRNA4 gene, which encodes for the nicotinic ACh receptor subunit, may cause the development of nocturnal frontal lobe epilepsy, while pilocarpine, a nonselective muscarinic receptor agonist, may initiate seizures and status epilepticus in experimental animals." (PMID 33810231, 2021).
psychosis (5 papers, 2013 to 2025). "CHRM3 was co-expressed with three psychosis risk genes (GABAG2, CHRNA4, and HRH3) in the thalamus and other human brain tissues and mouse GABAergic neurons." (PMID 31740666, 2019).
alcoholism (4 papers, 2013 to 2019). "An additional study identified a CHRNA4 SNP associated with alcoholism in a small Korean population." (PMID 23641218, 2013).
dementia (4 papers, 2020 to 2024). Loss of intellectual abilities interfering with an individual's social and occupational functions. "Another class encountered in trials was represented by dementia therapeutic agents acting on neuronal acetylcholine receptor subunit alpha-4, neuronal acetylcholine receptor subunit beta-2, neuronal acetylcholine receptor subunit alpha-7 (gene names: CHRNA4, CHRNB2, CHRNA7, respectively)." (PMID 36467081, 2022).
Insulin resistance (4 papers, 2016 to 2021). Increased resistance towards insulin, that is, diminished effectiveness of insulin in reducing blood glucose levels. "Loss or downregulation of Nr4a3 (Log2FC = −5.87), Scd1 (Log2FC = −2.24), Chrna4 (Log2FC = −4.23), and Fabp5 (Log2FC = −3.82) increase glucose intolerance, insulin resistance, diet-induced fatty liver disease, and cholinergic anti-inflammatory pathways." (PMID 35004828, 2021).
melanoma (4 papers, 2013 to 2023). A malignant, usually aggressive tumor composed of atypical, neoplastic melanocytes. "Results revealed that CHRNA4 (HR 4.263, 95% CI 1.612–11.272, p = 0.003), CHRNG (HR 8.430, 95% CI 1.510–47.067, p = 0.015), melanoma ulceration (HR 1.627, 95% CI 1.061–2.496, p = 0.026), and N2&3 stage (HR 3.709, 95% CI 2.257–6.095, p < 0.001) were independent poor prognostic factors." (PMID 37404751, 2023).
Epileptic encephalopathy (3 papers, 2019 to 2022). A condition in which epileptiform abnormalities are believed to contribute to the progressive disturbance in cerebral function. "In this region, three genes including KCNQ2, EEF1A2, and CHRNA4 were related to dominant epileptic encephalopathy, and KCNQ2 is the key gene." (PMID 35557555, 2022).
age (2 papers, 2021 to 2025). A temporal measurement of the time period elapsed since an identifiable point in the life cycle of an organism. "Thus, decreased Chrna4 levels in FKO livers may attenuate acetylcholine-driven cytokine production and limit immune cell–hepatocyte crosstalk, thus suggesting a protective effect against age-related inflammatory and fibrotic liver changes." (PMID 41516073, 2025).
colon cancer (2 papers, 2015 to 2025). "Additionally, CNV analysis indicated a significant increase in the proportion of CNVs for CHRNA4 and USP42 in colon cancer, while an increase in CNVs for FURIN and FES was noted in rectal cancer." (PMID 40426913, 2025).
epilepsy syndrome (2 papers, 2013 to 2020). A syndrome that has a characteristic cluster of clinical features and/or lectroencephalographic (EEG) findings that reflect underlying epileptic activity. "Several studies have indicated the CHRNA4 as strong candidates for the understanding of genetic factors related to epilepsy syndrome." (PMID 33281884, 2020).
focal epilepsy (2 papers, 2021 to 2023). A seizure caused by a localized disorder. "In addition, clinical data demonstrated that mutations in CHRNA4 may be a novel gene causing genetic or focal epilepsy with febrile seizures and familial partial epilepsy with variable foci, it aims to broaden the genotypic-phenotypic spectrum of combined epileptic in CHRNA4." (PMID 33924731, 2021).
migraine (2 papers, 2021 to 2024). "In this study, we further examined the channelopathic nature of a migraine through the analysis of common genetic variants in three selected ion channel or transporter genes: SLC4A4, SLC1A3, and CHRNA4." (PMID 38927733, 2024).
congestive heart failure (1 paper, 2020). Failure of the heart to pump a sufficient amount of blood to meet the needs of the body tissues, resulting in tissue congestion and edema. "And it is reported that CHRNA4 may participate in congestive heart failure." (PMID 33281884, 2020).
hepatocellular carcinoma (1 paper, 2017). A malignant tumor that arises from hepatocytes. "Although some evidence has suggested that individuals with reduced metabolic function of CYP2A6 smoke fewer cigarettes and have a shorter smoking duration, the functionality of CHRNA4 in both normal liver and hepatocellular carcinoma still need to be further intensively investigated." (PMID 28583088, 2017). "We found that the expression level of CHRNA4 and nicotine metabolism genes, including CYP2A6, FMO3, UGT2B7 were dramatically down-regulated in human hepatocellular carcinoma, suggesting disrupted nicotine metabolism in hepatocellular carcinoma." (PMID 28583088, 2017).
liver cancer (1 paper, 2017). An epithelial or non-epithelial malignant neoplasm that arises from the liver. "Smoking is generally believed to be a risk factor for liver cancer, we further examined the expression of CHRNA4 and nicotine metabolism - related genes in liver cancer samples by using TCGA liver hepatocellular carcinoma transcriptome data." (PMID 28583088, 2017).
liver inflammation (1 paper, 2025). "A recent study has demonstrated that Chrna4 expression is elevated in metabolic dysfunction-associated steatohepatitis (MASH) and that its activation promotes pro-inflammatory cytokine production contributing to the progression of liver inflammation." (PMID 41516073, 2025).
lung adenocarcinoma (1 paper, 2013). A carcinoma that arises from the lung and is characterized by the presence of malignant glandular epithelial cells. "CDK13, BMP1, RNF13, MAT2A, CHRNA4 are also among the genes in Merged-module whose over-expression has been reported in different cancers, however, their over-expression has been demonstrated in lung adenocarcinoma in this study." (PMID 23874428, 2013).
self-limited familial infantile epilepsy (1 paper, 2024). This syndrome is characterized by the onset of seizures between 3 and 20 months of age (peak 6 months). "In particular, several mutations were found in CHRNA4 and CHRNB2, whereas only four variants were reported in CHRNA2, including one in a family with self-limited familial infantile epilepsy (SeLFIE), previously known as benign familial infantile seizures (BFISs)." (PMID 39596607, 2024).
cancer (56 papers, 2009 to 2026). A tumor composed of atypical neoplastic, often pleomorphic cells that invade other tissues. "Still, our comprehensive bioinformatics analysis of cancer–nerve crosstalk-associated genes in SKCM constructed a valuable prognostic model based on eight genes (GRIN3A, CCR2, CHRNA4, CSF1, NTN1, ADRB1, CHRNB4, and CHRNG) and common clinical characteristics." (PMID 37404751, 2023). "Previous studies have shown that polymorphisms in the chromosome region containing three nAChR genes (CHRNA3, CHRNA4, and CHRNA5) are associated with an increased cancer risk." (PMID 35892574, 2022). "Interestingly, CHRNA4 expression was low in matched normal liver cells from patients with cancer." (PMID 28583088, 2017). "However, CHRNA4 was significantly down-regulated in cancer-matched normal livers." (PMID 28583088, 2017).
tumor (53 papers, 2009 to 2026). "Five genes - CHRNA4, AC084026.2, AC015910.1, MEI4, and AC025062.3 - exhibited decreased expression levels in tumor samples compared to normal tissue." (PMID 40356901, 2025). "In particular, the expression of the CHRM1, CHRNA2, CHRNA4, CHRNA6, CHRNA7, and CHRNB2 genes was increased in samples from the tissue of the anterior edge of the tumor." (PMID 38393158, 2024). "Nicotine exposure alone and cisplatin treatment alone appeared to increase the mRNAs of CHRNA4, CHRNB2, and CHRNA3 in the tumor samples, while their combination resulted in further increases." (PMID 35565402, 2022). "The downregulation of CHRNA4, AC084026.2, AC015910.1, MEI4, and AC025062.3 in tumor samples suggests that these genes may act as tumor suppressors, while the upregulation of the other identified hub genes implies a possible oncogenic role." (PMID 40356901, 2025). "The levels of mRNAs of CHRNA4, CHRNB2, and CHRNA3 in the tumor tissues were also quantified." (PMID 35565402, 2022).
psychiatric disorder (4 papers, 2013 to 2023). A disorder characterized by behavioral and/or psychological abnormalities, often accompanied by physical symptoms. "Thus, further studies could evaluate all these different endophenotypes in an attempt to elucidate the mechanisms by which CHRNA4 polymorphisms might modulate psychiatric disorders, ND, and smoking cessation." (PMID 25774163, 2015).
CHRNA4 also shares sentences with these, for which no sentence is quoted: myasthenia gravis (25 papers); breast cancer (16); infection (15); congenital myasthenic syndrome (10); COVID-19 (10); neurological diseases (10); neuroblastoma (7); respiratory failure (6); autoimmune disease (5); pancreatic cancer (5); alcohol abuse (4); cognitive decline (4); cognitive disorder (4); ischemia (4); neurodegenerative disease (4); neuropathic pain (4); Obesity (4); rhabdomyosarcoma (4); small cell lung carcinoma (4); anxiety disorder (3); attention deficit-hyperactivity disorder (3); autism (3); channelopathy (3); chronic obstructive pulmonary disease (3); cystic fibrosis (3); Dyskinesia (3); emphysema (3); head and neck cancer (3); Hypertension (3); Intellectual disability (3).
A further 121 diseases each share a sentence with CHRNA4 in 3 papers or fewer.